PTPRK (protein tyrosine phosphatase receptor type K)
Diseases named in the same sentence as PTPRK in open-access papers (continued):
Sharing a sentence is not in itself a finding about the gene and the disease.
cancer (28 papers, 2012 to 2025). A tumor composed of atypical neoplastic, often pleomorphic cells that invade other tissues. "Periostin and PTPRK have previously been reported to be associated with drug resistance in cancer and cancer stem cells." (PMID 40518514, 2025). "PTPRK regulates cell–cell adhesion but is also reported to regulate numerous cancer-associated signalling pathways." (PMID 38904097, 2024). "The PTPRK gene is associated with an increased risk of neuropsychiatric diseases and cancer, and the literature provided evidence that the PTPRK gene is associated with the risk of AD." (PMID 35069181, 2021). "Together with its subfamily members PTPRU and PTPRK, they are amongst the most frequently mutated PTPs in a number of cancer types." (PMID 27586084, 2016). "Interestingly, previous studies have also suggested association between altered PTPRK genomic status and poor survival in other cancers." (PMID 23696788, 2013). "Indeed, loss of PTPRK activity has been observed in pancreatic cancer, primary CNS lymphoma and melanoma, and is associated with poor survival of cancer patients." (PMID 23696788, 2013). "Thus, PTPRK modulates cell–cell adhesion as well as numerous cancer-associated signalling pathways." (PMID 38904097, 2024). "Taken together, our data support a role for PTPRK in wound healing and injury repair in cancer cells and in mice." (PMID 38904097, 2024). "It seems to be supported by others, as a restoration of PTPRK expression in cancer cell lines resulted in a reduction of phosphorylated extracellular signal-regulated kinases 1 and 2 (Erk 1/2), protein kinase B, (Akt), STAT3, and STAT5." (PMID 33921897, 2021). "The three main conclusions of this study are i) that the transmembrane phosphatase PTPRK, whose gene is found in prominent cancer-related fusion events with the ZNRF3 negative regulator RSPO3, is itself a positive regulator of ZNRF3." (PMID 31934854, 2020). "PTPRK, which is located in the frequently deleted gene region 6q22.2-22.3 of various tumors, was identified as a candidate tumor suppressor gene in cancer research." (PMID 30838170, 2019). "Intriguingly, depletion of PTPRK significantly reduced sensitivity to the anti‐cancer drug oxaliplatin and was accompanied by up‐regulation of phosphorylation of Bad, a downstream target of AKT." (PMID 30947381, 2019). "Collectively, these results indicate that PTPRK‐mediated prohibition of the pro‐oncogenic CD133–AKT pathway improves oxaliplatin sensitivity of CD133‐expressing cancer cells." (PMID 30947381, 2019). "In silico analyses of The Cancer Genome Atlas data sets revealed consistent correlations between the expression of the transcripts encoding LRIG1 and its interactors ZBTB16 and PTPRK and inverse correlations between the transcripts encoding LRIG1 and GLRX3." (PMID 29317492, 2018). "EGFR and β-catenin signaling are the only two major pathways that have been studied as potential PTPRK targets in few published cancer studies." (PMID 23696788, 2013). "Such opposing effects of PTPRK in different cancers suggest a cancer-specific role." (PMID 38999976, 2024). "Additionally, the lower PTPRK expression was observed in Aldehyde Dehydrogenase 1 Family Member A1 (ALDH1A1) positive cancer stem cells (CSCs) population, suggesting the role of PTPRK downregulation in primary as well as acquired resistance to cytotoxic drugs." (PMID 31027318, 2019). "Recent studies have shown that PTPRK is frequently downregulated in many human cancers." (PMID 30838170, 2019). "Some changes in PTPRK expression can have an influence on cancer development." (PMID 31027318, 2019). "PTPRK negatively regulates the transcriptional activity of ß-catenin in cancer cells." (PMID 24416132, 2014). "Based on these limited studies, it could be speculated that the processed PTPRK fragment in the cytoplasm, once freed from the membrane, translocates to the nucleus and may contribute to cancer phenotype via undefined mechanisms." (PMID 23696788, 2013).
cancer (continued). "Interestingly, the PTPRK locus (6q22–23) is a common region of allelic deletion at chromosome 6 in several cancers." (PMID 23696788, 2013). "Therefore, a positive role of PTPRK is supposed in regulating cancer-cell induced angiogenesis." (PMID 38999976, 2024). "However, expression of PTPRK was observed in some other cancers." (PMID 31027318, 2019). "Although PTPRK supports normal tubule formation, it seems to inhibit tubule formation by suppressing pathways induced by VEGF, FGF, and cancer cells." (PMID 38999976, 2024). "Human receptor-type PTP kappa (PTPRK or R-PTP-kappa) is expressed by various normal cell types, including vascular ECs; however, several cancer cell lines show aberrant expression of PTPRK." (PMID 38999976, 2024). "The levels of several mRNAs that code for surface proteins with roles in cancer were similarly upregulated, including ALK, PTPRM, PTPRF, PTPRK, and SVEP1." (PMID 39335212, 2024). "Here we identify the tumor suppressor Protein tyrosine phosphatase receptor-type kappa (PTPRK), as a Wnt inhibitor in human cancer cells and in the Spemann organizer of Xenopus embryos." (PMID 31934854, 2020). "Cancer has been likened to a ‘wound that will not heal’, and in this way PTPRK KO cells are in a constant state of wound healing." (PMID 38904097, 2024). "In addition, we observed that PTPRF was co-amplified or co-deleted with PTPRK and PTPN3 in various cancers." (PMID 36341348, 2022). "Additionally, PTPRK and LRIG1 expression was consistently correlated in a wide range of cancer types and normal tissues." (PMID 29317492, 2018).
neurological disorders (1 paper, 2016). "PTPRK is known to show a key role in other neurological disorders." (PMID 27997584, 2016).
PTPRK also shares sentences with these, for which no sentence is quoted: melanoma (4 papers); lipoma (3); prostate carcinoma (3); liver cancer (2); adenoma (1); autoimmune disease (1); breast and ovarian cancer (1); breast tumors (1); gastric tumors (1); laryngeal squamous cell carcinoma (1); leukemia (1); lymphoma (1); microcephaly (1); multiple sclerosis (1); preeclampsia (1); rhabdoid tumor (1); T-cell lymphoma (1); thyroid cancer (1).